ACER3 (alkaline ceramidase 3)
Description:
Endoplasmic reticulum and Golgi ceramidase that catalyzes the hydrolysis of unsaturated long-chain C18:1-, C20:1- and C20:4-ceramides, dihydroceramides and phytoceramides into sphingoid bases like sphingosine and free fatty acids at alkaline pH. Ceramides, sphingosine, and its phosphorylated form sphingosine-1-phosphate are bioactive lipids that mediate cellular signaling pathways regulating several biological processes including cell proliferation, apoptosis and differentiation. Controls the generation of sphingosine in erythrocytes, and thereby sphingosine-1-phosphate in plasma. Through the regulation of ceramides and sphingosine-1-phosphate homeostasis in the brain may play a role in neurons survival and function (By similarity). By regulating the levels of pro-inflammatory ceramides in immune cells and tissues, may modulate the inflammatory response (By similarity).
Synonyms: aPHC; PHCA; FLJ11238; PLDECO
Tractability: Small molecule: a structure with a bound ligand is known. Antibody: UniProt predicts a signal peptide or a membrane-spanning region.
Gene: Protein-coding gene on chromosome 11 (76,860,859 to 77,026,797, forward strand). Ensembl gene ENSG00000078124.
Subcellular location: Endoplasmic reticulum membrane; Golgi apparatus membrane
Pathways (Reactome):
Metabolism: Sphingolipid catabolism
Gene Ontology:
Molecular function: calcium ion binding; N-acylsphingosine amidohydrolase activity; zinc ion binding
Biological process: ceramide catabolic process; myelination; phytosphingosine biosynthetic process; positive regulation of cell population proliferation; regulation of programmed cell death; sphingosine biosynthetic process; ceramide metabolic process; inflammatory response; sphingolipid metabolic process
Cellular component: endoplasmic reticulum membrane; Golgi membrane; membrane
Genetic constraint (gnomAD): Loss-of-function variants: 6 observed, 14.54 expected, observed/expected ratio (o/e) 0.41, 90% interval 0.22 to 0.81. The upper end of that interval is the gene's LOEUF score, 0.81, which puts it in group 3 of 6, group 1 being the genes least tolerant of losing a copy. Missense variants: 88 observed, 113.41 expected, observed/expected ratio (o/e) 0.78, 90% interval 0.65 to 0.93. Synonymous variants: 49 observed, 42.97 expected, observed/expected ratio (o/e) 1.14, 90% interval 0.91 to 1.45.
Homologues: Orthologues: chimpanzee ACER3 (99% identical), macaque ACER3 (98% identical), dog ACER3 (96% identical), rabbit ACER3 (95% identical), guinea pig ACER3 (91% identical), pig ACER3 (91% identical), mouse Acer3 (88% identical), rat Acer3 (88% identical), tropical clawed frog acer3 (76% identical), zebrafish acer3 (67% identical). Paralogues in human: ACER2 (27% identical), ACER1 (20% identical).
Diseases named in the same sentence as ACER3 in open-access papers:
ACER3 is named in the same sentence as 39 diseases in open-access papers, as found by Europe PMC text mining. Sharing a sentence is not in itself a finding about the gene and the disease. The quoted sentences say what the papers report.
leukodystrophy (7 papers, 2018 to 2025). Leukodystrophies are a group of rare, progressive, metabolic, genetic diseases that affect the brain, spinal cord and often the peripheral nerves. "Background and aims: Biallelic variants in Alkaline Ceramidase 3 (ACER3) have recently been linked to early‐onset leukodystrophy in 3 case reports describing 5 families with 7 patents." (PMID 40542581, 2025). "Recessively inherited loss-of-function mutations in alkaline ceramidase 3 (ACER3) also result in increased dihydrosphingolipid formation and a leukodystrophy phenotype (MIM #617762)." (PMID 36976648, 2023). "We demonstrated that ACER3 deficiency results in Purkinje cell degeneration in mice and that a point mutation of ACER3 leads to progressive leukodystrophy in early childhood in humans." (PMID 36048828, 2022). "Merely only two ACER3 mutations in cases of progressive leukodystrophies have been reported thus far." (PMID 34281620, 2021). "In 2016, Edverdson and coworkers investigated the genetic background of leukodystrophy in a patient through exome sequencing and found that the patient was homozygous for a p.E33G mutation in alkaline ceramidase ACER3." (PMID 31817238, 2019). "Remarkably, this discovery provides molecular insights into the E33G ACER3 mutation carried by patients suffering leukodystrophy, which results in the loss of ACER3 ceramidase activity despite similar level of expression than in control membrane preparations." (PMID 30575723, 2018). "Also, mutations in the alkaline ceramidase 3 (ACER3) cause leukodystrophy." (PMID 37890668, 2023). "Due to the defect in ACER3, long-chain ceramides and dihydroceramide accumulated in the plasma and brain of the leukodystrophy patient." (PMID 31817238, 2019). "Furthermore, we uncover how a single point mutant (E33G) results in the destabilization of the calcium binding site, providing a molecular explanation for the ACER3 mutant dysfunction leading to leukodystrophy in human." (PMID 30575723, 2018). "The clinical follow-ups and serial imaging in our patients indicated that ACER3-related leukoencephalopathy is more compatible with a primary neuronal disorder rather than a leukodystrophy." (PMID 34281620, 2021). "Given these imaging findings, it seems that ACER3-related leukoencephalopathy could not be considered as a true leukodystrophy or at least proving this requires more research." (PMID 34281620, 2021).
colitis (5 papers, 2016 to 2024). Inflammation of the colon. "Acer3 deficiency has been shown to increase the local and systemic production of proinflammatory cytokines and exacerbated colitis in the DSS-induced murine colitis model." (PMID 38839750, 2024). "Loss of neutral ceramidase (nCDase) or alkaline ceramidase 3 (ACER3) increased susceptibility to colitis, and ACER 3 significantly increased CAC in an AOM/DSS model." (PMID 38398179, 2024). "Although a specific increase of C18:1‐ceramides via alkaline ceramidase 3 deficiency exacerbates inflammation in experimental colitis 48, distinct roles of ceramides with other acyl chain lengths in IBD have not been explored." (PMID 28699686, 2017). "Acer3 deficiency also aggravated colonic dysplasia in a mouse model of colitis-associated colorectal cancer." (PMID 26938296, 2016). "During acute colitis, we found that Acer3 deficiency worsened epithelial damage and epithelial apoptosis." (PMID 26938296, 2016). "PAS/AB staining showed that upon colitis induction, Acer3−/− mice had a higher loss of mucous-producing epithelial cells, a characteristic lesion of DSS-induced colitis, than Acer3+/+ mice." (PMID 26938296, 2016). "As systemic inflammatory manifestations, including white blood cell elevation and spleen enlargement, have been observed in acute DSS-induced colitis, we examined Acer3 deficiency in the systemic inflammatory response during colitis." (PMID 26938296, 2016). "In the mouse model of dextran sulfate sodium-induced colitis, Acer3 deficiency augmented colitis-associated elevation of colonic C18:1-ceramide and pro-inflammatory cytokines." (PMID 26938296, 2016). "More importantly, we found that Acer3 deficiency aggravates dextran sulfate sodium (DSS)-induced colitis and colitis-associated colorectal cancer (CAC) in a murine model." (PMID 26938296, 2016). "Based on these observations, we postulated that Acer3 deficiency aggravates colitis by upregulating pro-inflammatory cytokines in myeloid cells and CECs as well as apoptosis of CECs in a C18:1-ceramide-dependent manner." (PMID 26938296, 2016). "As Acer3 deficiency promoted LPS-induced cytokine upregulation in cells, we determined if Acer3 deficiency also affected inflammatory cytokines in the colon tissues of mice with colitis." (PMID 26938296, 2016). "During colitis, both immune cells and CECs could be exposed to LPS released from gut microbes;17, 18, 20 therefore, colitis-associated downregulation of Acer3 in the colon may be triggered by LPS." (PMID 26938296, 2016). "We also showed that C18:1-ceramide was also elevated in colon with a concomitant downregulation of Acer3 during colitis induction in WT mice, and the elevation of C18:1-ceramide was augmented by Acer3 deficiency." (PMID 26938296, 2016). "Acer3−/− mice that survived DSS treatment showed more severe colitis, as evidenced by a greater colon shortening, higher levels of inflammatory cytokines (Il-1β, Il-6, Il-23a and Tnf-α), higher MPO activity and more severe pathological manifestations." (PMID 26938296, 2016). "Colitis characteristics, including bleeding and diarrhea, were monitored in Acer3−/− and Acer3+/+ mice during and after colitis induction." (PMID 26938296, 2016). "We found that compared with Acer3+/+ mice, Acer3−/− mice had higher colitis activity scores with severe diarrhea and bleeding." (PMID 26938296, 2016). "More importantly, we revealed that Acer3 was downregulated in colon during acute colitis." (PMID 26938296, 2016). "The results revealed that Acer3 knockout significantly augmented the colitis-induced increases in the mRNA levels of Il-1β, Il-6, Tnf-α and Il-23a in colon, although Acer3 deficiency did not affect the basal mRNA levels of these inflammatory cytokines." (PMID 26938296, 2016). "This excludes the possibility that Acer3 deficiency exacerbates colitis by disrupting the epithelial barrier." (PMID 26938296, 2016).
colitis (continued). "Our in vitro findings demonstrated that LPS suppressed Acer3 in both immune cells and CECs, so we postulated that the downregulation of Acer3 in colon may also occur in these cell types during colitis." (PMID 26938296, 2016). "After DSS withdrawal, Acer3−/− mice recovered from colitis more slowly than Acer3+/+ mice." (PMID 26938296, 2016). "After necropsy, examination of the colon found that during the acute colitis Acer3−/− mice had earlier and greater colonic shortening, compared with Acer3+/+ mice, higher scores of colonic epithelial damage and inflammatory infiltration, and a greater colonic myeloperoxidase (MPO) activity." (PMID 26938296, 2016). "Interestingly, Acer3 deficiency did not affect colitis-associated increases in this SM species in the colon." (PMID 26938296, 2016). "First, we determined if Acer3 and its regulated C18:1-ceramide were altered in mouse colons in response to DSS-induced colitis." (PMID 26938296, 2016).
hepatocellular carcinoma (4 papers, 2022 to 2025). A malignant tumor that arises from hepatocytes. "Alkaline ceramidase 3 (ACER3) was reported to promote proliferation and reduced cell death in hepatocellular carcinoma cells and was inversely correlated with survival in patients." (PMID 40497995, 2025). "Knockdown of ACER3 has been shown to decrease cancer cell growth and increase apoptosis in hepatocellular carcinoma patients." (PMID 38235387, 2023). "ACER3 promotes the growth of hepatocellular carcinoma cells through the S1P/S1PR2/PI3K/AKT signaling pathway and may be a potential therapeutic target for the treatment of liver cancers." (PMID 38235387, 2023). "More importantly, an article related to hepatocellular carcinoma has assessed the role of ACER3 in tumor development and revealed that ACER3 overexpression impairs radiosensitivity and apoptosis but aggrandize metastasis of HCC cells." (PMID 34817752, 2022). "In addition, NC regulates colon cancer initiation and development, ACER3 promotes growth of hepatocellular carcinoma cells and supports AML survival, and ACER2 is involved in hepatocellular carcinoma and estrogen receptor-positive breast tumorigenesis." (PMID 38369184, 2024).
acute myeloid leukemia (3 papers, 2018 to 2022). Acute myeloid leukemia (AML) is a group of neoplasms arising from precursor cells committed to the myeloid cell-line differentiation. "ACER3 often expresses highly in the malignant progression of tumors, such as acute myeloid leukemia." (PMID 34817752, 2022). "Similarly, ACER3 deficiency decreased acute myeloid leukemia (AML) cell growth and increased apoptosis in the AML cells via limiting AKT signaling." (PMID 35565311, 2022). "Moreover, in vitro results obtained in human cells revealed that ACER3 contributes to acute myeloid leukemia (AML) pathogenesis." (PMID 30575723, 2018).
cerebellar ataxia (3 papers, 2015 to 2023). A neurological syndrome characterized by clumsy and uncoordinated movement of the limbs, trunk, and cranial muscles. "In this study we found that Acer3 is upregulated with age in the mouse brain and blocking Acer3 upregulation elevates the levels of ceramides while reducing S1P levels in the brain, thereby resulting in Purkinje cell loss and cerebellar ataxia." (PMID 26474409, 2015). "Because dyshomeostasis of sphingolipids could lead to a defect in myelination, which has been linked to various neurological disorders including cerebellar ataxia, we tested if Acer3 deficiency impaired myelination in the cerebellum in mice at 8 months of age." (PMID 26474409, 2015). "It has been demonstrated in mice that ACER3 plays an important protective role, since it controls the homeostasis of ceramides and their derivatives such as S1P, avoiding the appearance of neurological disorders such as cerebellar ataxia." (PMID 32822435, 2020). "In this study, we demonstrate for the first time that age-dependent upregulation of Acer3 plays a key role in sustaining the homeostasis of both ceramides and S1P in the aging mouse brain; thus protecting PCs from premature degeneration and hence from cerebellar ataxia." (PMID 26474409, 2015).
nonalcoholic steatohepatitis (3 papers, 2020 to 2022). "Similarly, the abnormally elevated ACER3 expression is measured in nonalcoholic steatohepatitis, and functionally inhibiting ACER3 could protect livers against inflammation and fibrosis through depressing oxidative stress." (PMID 34817752, 2022).
steatosis (3 papers, 2020 to 2023). Increased lipid within the cytoplasm of cells. "To this end, we challenged the Acer3 null mice and their wild-type littermates with PEWD, and examined if Acer3 deficiency affected pathogenesis of NASH in terms of steatosis, inflammatory infiltration, and fibrosis." (PMID 31949129, 2020). "Taken together, these data suggest that Acer3 deficiency alleviates early inflammation and fibrosis without affecting steatosis in NASH mice." (PMID 31949129, 2020). "Steatosis in L02 cell was not affected by knockdown of ACER3 after palmitate treatment." (PMID 31949129, 2020). "Knocking out Acer3 was found to augment PEWD-induced elevation of C18:1-ceramide and alleviate early inflammation and fibrosis but not steatosis in mouse livers with NASH." (PMID 31949129, 2020).
colorectal cancer (2 papers, 2016 to 2023). A primary or metastatic malignant neoplasm that affects the colon or rectum. "First, significant differences in gene expression between normal tissue and colorectal cancer tissue were observed for ASAH1, ACER3, CERS2, and CERS6." (PMID 37758931, 2023).
glioma (2 papers, 2022). A benign or malignant brain and spinal cord tumor that arises from glial cells (astrocytes, oligodendrocytes, ependymal cells). "Afterwards, ACER3, confirmed as a target of miR-1277-5p, was found to involve in glioma development." (PMID 34817752, 2022). "When evaluating ACER3 expression in glioma, it was identified that ACER3 was high-expressed in glioma tissues and cell lines." (PMID 34817752, 2022). "All in all, our research has determined the mechanism by which LINC01087 accelerated the growth of glioma cells via downregulating miR-1277-5p and upregulating ACER3." (PMID 34817752, 2022). "In contrast, there was no signficant correlation of elevated expression of other ceremidases (ASAH2, ACER2, ACER3) with poor glioma patient outcomes." (PMID 35741006, 2022). "The LINC01087 and ACER3 expression was in up-regulation and the miR-1277-5p expression was in down-regulation in clinical glioma samples." (PMID 34817752, 2022). "For these reasons, we examined the prognostic value of LINC01087 in glioma and also explored whether LINC01087/miR-1277-5p/ACER3 axis could modulate the biological activities of glioma cells." (PMID 34817752, 2022). "In this research, we evaluated the fundamental effects of LINC01087/miR-1277-5p/ACER3 axis in glioma cell growth, and attained the main observation illustrating that LINC01087 facilitated the biological behaviors of glioma cells by binding to miR-1277-5p to silence ACER3." (PMID 34817752, 2022). "In short, LINC01087-mediated pro-tumorigenesis in glioma could be reduced by overexpressing miR-1277-5p or suppressing ACER3." (PMID 34817752, 2022). "Moreover, rescue assays reveal that miR-1277-5p overexpression (or ACER3 overexpression) reversed the effects of LINC01087 upregulation (or miR-1277-5p upregulation) on glioma cells." (PMID 34817752, 2022). "However, much more efforts are still required to explore the downstream signaling pathways related to the progression of glioma mediated by the LINC01087/miR-1277-5p/ACER3 axis." (PMID 34817752, 2022). "ACER3 expression was raised in glioma, and knocking down ACER3 could restrain the malignant phenotypes of gliomas while overexpressing ACER3 restrained the effects of restored miR-1277-5p on glioma cells." (PMID 34817752, 2022). "The integral action of LINC01087/miR-1277-5p/ACER3 axis in glioma was further evaluated." (PMID 34817752, 2022). "Briefly, silencing ACER3 limited the malignant phenotype of glioma cells." (PMID 34817752, 2022). "Pearson analysis declared that ACER3 expression was negatively correlated with miR-1277-5p expression, but positively correlated with LINC01087 expression in glioma tissue." (PMID 34817752, 2022). "Glioma patients after preoperative MRI diagnosis were enrolled, and LINC01087, microRNA (miR)-1277-5p, and alkaline ceramidase 3 (ACER3) levels were tested in glioma cancer tissue." (PMID 34817752, 2022). "LINC01087 has prognostic significance in glioma and silencing LINC01087 deters glioma development through elevating miR-1277-5p to reduce ACER3 expression." (PMID 34817752, 2022).
asthma (1 paper, 2024). "The ceRNA network suggested that SNHG9-hsa-miR-615-3p-ACER3 may be implicated in asthma." (PMID 38297226, 2024). "The MCODE analysis identified a key module in the network, including three hub genes (ASAH1, ACER3 and SGPP1), all of which were downregulated genes and strongly linked to asthma." (PMID 38297226, 2024). "Among these genes, ASAH1, ACER3, and SGPP1 were identified as potential diagnostic biomarkers for asthma." (PMID 38297226, 2024). "Moreover, mTORC1 signaling, adipogenesis, MYC target v1, protein secretion, and fatty acid metabolism were significantly influenced by increased ACER3 expression in asthma." (PMID 38297226, 2024). "ASAH1, ACER3 and SGPP1 might be diagnostic biomarkers for asthma, and are associated with increased immune system activation." (PMID 38297226, 2024). "Overall, SNHG9, hsa-miR-615-3p and ACER3 might be viewed as effective therapeutic targets for asthma." (PMID 38297226, 2024). "Within the ceRNA network, SNHG9-hsa-miR-615-3p-ACER3, hsa-miR-212-5p and hsa-miR-5682 may play crucial roles in asthma pathogenesis." (PMID 38297226, 2024). "In addition, SNHG9-hsa-miR-615-3p-ACER3 might be involved in asthma pathogenesis, and hsa-miR-212-5p and hsa-miR-5682 could be viewed as effective therapeutic targets for asthma." (PMID 38297226, 2024). "Three downregulated LMRGs (ASAH1, ACER3 and SGPP1) were identified as hub genes for asthma, which were validated in GSE143192." (PMID 38297226, 2024). "In addition, SNHG9-hsa-miR-615-3p-ACER3 may be viewed as effective therapeutic targets for asthma." (PMID 38297226, 2024). "The specific role of ACER3 in asthma has not been reported, and future studies are required to further explore the connection between ACER3 and asthma." (PMID 38297226, 2024). "Thus, we hypothesized that individuals with downregulated LMRGs (ASAH1, ACER3 and SGPP1) may be liable to mediate the immune response, and more easily develop asthma." (PMID 38297226, 2024).